SNORD34 (small nucleolar RNA, C/D box 34)
Synonyms: U34; RNU34
Gene: Small nucleolar RNA gene on chromosome 19 (49,490,904 to 49,490,974, forward strand). Ensembl gene ENSG00000202503.
Gene Ontology:
Biological process: RNA processing
Cellular component: nucleolus
Homologues: Orthologues: chimpanzee SNORD34 (97% identical), macaque SNORD34 (94% identical), pig SNORD34 (89% identical), dog SNORD34 (87% identical), mouse Snord34 (82% identical), guinea pig SNORD34 (80% identical), rabbit SNORD34 (80% identical), rat LOC120100340 (80% identical), rat Snord34 (79% identical), tropical clawed frog SNORD34 (62% identical), tropical clawed frog SNORD34 (56% identical).
Diseases named in the same sentence as SNORD34 in open-access papers:
SNORD34 is named in the same sentence as 2 diseases in open-access papers, as found by Europe PMC text mining. Sharing a sentence is not in itself a finding about the gene and the disease.
SNORD34 shares sentences with these, for which no sentence is quoted: glioblastoma multiforme (1 paper); leukemia (1).